CCR1 (C-C motif chemokine receptor 1)
Diseases named in the same sentence as CCR1 in open-access papers (continued):
Sharing a sentence is not in itself a finding about the gene and the disease.
tumor (continued). "Nevertheless, we also note that integrin activation appeared as a universal mechanism detected in pre-activation cells of tumor core and periphery, while CD44 and NRP1/2 activity was higher in tumor core and chemokine receptors CCR1 and CSF1R were higher ranked in the tumor periphery." (PMID 33177572, 2020). "CCR1 was expressed in ID8 and SKOV3ip.1 derived tumor tissue." (PMID 32963283, 2020). "Moreover, it was recently found that CCL15 induced the recruitment of CCR1+ CD14+ monocytes to HCC invasive margin; in turn, monocytes suppressed the anti-tumor immune response and promoted tumor metastasis." (PMID 31991677, 2020). "Similar studies of MM mouse models showed that the CCR1 antagonist CCX721 could decrease osteoclastic activity, osteolytic lesions and tumor formation." (PMID 31572390, 2019). "Likewise, treatment of a humanized MM mouse model with the CCR1-specific inhibitor MLN3897, led to increased osteoblast function, decreased osteoclast formation, as well as reduced tumor burden." (PMID 31572390, 2019). "The relative roles of CCR3 (as opposed to CCR1) in metastasis and tumor growth in bone were not addressed and its potential importance in bone metastasis in vivo remains to be studied." (PMID 29930538, 2018). "Cancer cells grown orthotopically in the mammary gland of CCR5 null mice, but not CCR1 null mice, showed dramatically reduced tumor growth, compared to control wild-type (WT) animals (P < 0.0001)." (PMID 27863423, 2016). "Collectively, these data imply that therapeutic inhibition of CCR1 and CCR2 could be a novel strategy to prevent metastatic tumor growth." (PMID 26275794, 2015). "Expression of CCR1 was detected in HT199, HT168 and WM983A tumor cell lines." (PMID 26320180, 2015). "However, there was no enhanced recruitment of Ccr1-/- monocytes in tumor bearing versus naïve Ccr1-/- mice." (PMID 39566333, 2025). "Furthermore, the simultaneous inhibition of CCR1 and CXCR2 expressed on myeloid cells can result in more robust suppression of tumor growth and metastasis, highlighting the potential of combinational therapeutic strategies targeting multiple chemokine receptors." (PMID 39795864, 2024). "In the present study, we used double-knockout mice for CCR1 and CXCR2 in BM transfer experiments, and discovered that simultaneous deletion of both CCR1 and CXCR2 entirely inhibited neutrophil mobilization, thereby significantly suppressing tumor growth and metastasis." (PMID 38750114, 2024). "We therefore hypothesize that CCR1 is not essential for the recruitment but is necessary for reprogramming of TAMs once they accumulate at the tumor." (PMID 36982211, 2023). "Then, we evaluated whether silencing of CCR1 and/or CCR5 was sufficient to inhibit tumor growth." (PMID 35064009, 2022). "Finally, we evaluated whether CCR1 and CCR5 blockade inhibited myeloid cell trafficking to the tumor." (PMID 35064009, 2022). "Indeed, we did not observe any changes in the phenotype or number of tumor-infiltrating lymphocytes in mice treated with CCR1 and CCR5 shRNAs but we observed a modification of phenotype and function of PMN-cells, macrophages, and DCs." (PMID 35064009, 2022). "In addition, the tumor tissue of the DEN/CCl4-treated WT mice shows a reduction of chemokine receptors levels compared to the surrounding tissue of the same mouse (Ccr5, Ccr2, Ccr7, Ccr1 and Cxcr4)." (PMID 35897689, 2022). "TAMs could independently stimulate tumor cell growth and migration via the CCL5/CCR1/CCR5 axis." (PMID 35646059, 2022). "The combination of a CCR1 antagonist, CCX9588, with an anti-PDL1 antibody has proven to be a promising therapeutic approach, as it resulted in synergistic antitumoral effects by inhibiting primary tumor growth and lung metastasis in an orthotopic breast cancer mouse model." (PMID 34575965, 2021).
tumor (continued). "cDC1 express XCR1, as well as CCR1 and CCR5, both of which bind CCL5 and have antitumor functions; they can attract and activate tumor-specific CD8 T cells, and internalize and transport tumor antigens to lymph nodes, where they may cross-prime CD8 T cells." (PMID 34936871, 2021). "In CCL9-expressing CMT93 colon carcinoma, CCR1+ neutrophils secrete MMP9 to foster cancer foci, and in late phases of tumor the neutrophils recruit fibrocytes or induce differentiation from monocytes to fibrocytes which secrete MMP2, accommodating tumor cell colonization." (PMID 31474975, 2019). "Interestingly, loss of CCR1 does not affect the recruitment of monocytes but, instead, prevents MAM-cancer cell interactions and subsequent retention of MAMs in the tumor-challenged lung." (PMID 30483271, 2018). "Additionally, neo-antigen load correlated with increased expression of the chemokines TNFRSF25, CCR1, and LTBR, which may serve as valuable targets in future tumor immunology studies." (PMID 29487705, 2018). "However, although expression of Ccl5 and its receptors Ccr1 and Ccr3 were not affected by IL-6Rα deficiency in CAC, expression levels of Ccl20 and of its unique receptor Ccr6 were reduced in knockout tumours." (PMID 29695802, 2018). "Notably, tumor growth in WT mice transplanted with CCR1 null (WT:CCR1-/-), or CCR5 null BM (WT:CCR5-/-) did not significantly differ from tumors growing in WT mice reconstituted with WT BM (WT:WT)." (PMID 27863423, 2016). "Indeed, the appearance of apoptotic tumor cells induces the migration of dendritic cells to the draining lymph nodes and eventually generates a specific cytotoxic T lymphocyte population in the draining lymph nodes by utilizing the CCL3-CCR5/CCR1 axis." (PMID 24966464, 2014). "Consistently, when CCR1 was knocked down in THP1 cells, co-culture with tumor cells overexpressing CCL16 no longer facilitated macrophage recruitment." (PMID 38274805, 2023). "While pretreatment with CCR1 and CCR5 antagonists significantly reduced the T cell chemotaxes to the lungs, spleen, and tumor, we did not observe any difference on the biodistribution of CD11b+ myeloid cells." (PMID 35064009, 2022). "In the same model, the lack of C-C motif chemokine receptor 1, the cognate receptor for CCL9, prevented the accumulation of MMP-expressing cells and significantly suppressed tumor invasion into the smooth muscle layer." (PMID 29720595, 2018). "Mechanistically, paracrine CCL5 from ovarian CSLCs activates the NF-κB signaling pathway in ovarian non-CSLCs via binding CCR1/3/5, thereby inducing EMT and tumor invasion." (PMID 25788271, 2015). "Blocking of chemokine receptor CCR2 but not CCR1, CCR3, CCR5, CCR7 or CXCR3 on CTL007 with Abs significantly inhibited tumor cell apoptosis." (PMID 21450101, 2011).
cancer (96 papers, 2009 to 2025). A tumor composed of atypical neoplastic, often pleomorphic cells that invade other tissues. "CCR1 overexpression has been described in several types of cancer and is associated with increased immunosuppressive cell infiltration and metastasis." (PMID 37895310, 2023). "C-C chemokine receptor type 1 (CCR1) is a mediator of neutrophil, monocyte, and lymphocyte recruitment in sites of inflammation, and, along with its ligands, it has been linked to cancer cell survival, migration, and invasion." (PMID 37509358, 2023). "CCL16 also causes the migration of cancer cells if they exhibit CCR1 expression." (PMID 33182504, 2020). "However, the most important pro-cancer function of CCL23 may be the induction of angiogenesis by activating CCR1 on vascular endothelial cells, a process associated with increased expression and secretion of matrix metalloproteinase (MMP)-2 from these cells." (PMID 33182504, 2020). "To validate the relevance of the Ccr1 chemokine axis during cancer progression we used the spontaneous lung metastasis model with subcutaneous injection of LLC1.1 cells." (PMID 39566333, 2025). "Regarding the key interaction between T cells and cancer cells, increased expression of ligand-receptor pairs MIF_TNFRSF10D, CD55_ADGRE5, CD226_NECTIN2, CCL3L1_CCR1, and CCL3_CCR1 was observed." (PMID 39986271, 2025). "CCL3 on CD8+ T cells was also predicted to interact with CCR1 or CCR5 on myeloid cells and CXCL13 on CD8+ T cells was predicted to interact with CXCR5 on B cells or ACKR4 on cancer-associated fibroblasts." (PMID 39478117, 2024). "TCGA database indicated that among several ligands, CXCL1, CXCL3, CXCL5, CXCL7 and CXCL8 (ligands for CXCR2) and CCL15 (ligand for CCR1) were particularly upregulated in CRC tissues compared with other cancers." (PMID 38750114, 2024). "During the course of cancer therapy, a high change rate of IL‐6, IL‐8, CXCL10, CCR1, and CCL5 was significantly associated with poor PFS." (PMID 37062076, 2023). "Macrophages in the milky spots promote colonization of cancer cells via secretion of C-C motif chemokine receptor 1 (CCR1) ligand." (PMID 37180125, 2023). "Chemokines, such as CCL28, CXCL8, and CXCL16, and chemokine receptors, including CCR1, CCR8, and CXCR2, were positively linked to DLAT expression in various cancers." (PMID 37199628, 2023). "Differential expression analysis of CCR1 in MACS-sorted cell fractions of ASC and MDA-MB-231 after 3D co-culture revealed that CCR1 expression was up-regulated to a significantly higher extent in the cancer cell fraction in comparison to the ASC fraction." (PMID 37444610, 2023). "Further proliferation assessment of unmodified CT26 cells utilized three different doses of CCR1 antagonist BX471 to determine the significance of the CCL9-targeted receptors for cancer cell proliferation." (PMID 37185750, 2023). "Specifically, chemokines such as CXCL9, CXCL10, and CXCL11 and chemokine receptors such as CXCR5, CCR4, CCR8, and CCR1 were positively correlated with IGF2BP3 expression in various cancer types." (PMID 36761737, 2023). "Intriguingly, CCR1 knockout macrophages displayed less physical interaction with the carcinoma cells, which suggests the existence of a juxtacrine interaction between carcinoma cells and TAMs." (PMID 36982211, 2023). "Increased expression of CC chemokines CCL3 (ligand for CCR1, CCR4, and CCR5), CCL4 (ligand for CCR5 receptor), and CCL5 (ligand for CCR1 and CCR5) have been implicated in cancer pathogenesis." (PMID 33390169, 2021). "Mechanistically we demonstrate that FAK-depletion in CAFs increases chemokine production, which via CCR1/CCR2 on cancer cells, activate protein kinase A, leading to enhanced malignant cell glycolysis." (PMID 32157087, 2020). "CCL5 participates in angiogenesis, which is associated with an increase in vascular endothelial growth factor (VEGF) expression in cancer cells and vascular endothelial cells via the activation of CCR1 and CCR5." (PMID 33076281, 2020).
cancer (continued). "To date, few studies have centered on the significance of the ligands of CCR1 as therapeutic targets in cancer therapies." (PMID 33182504, 2020). "The findings in our study, and safety and tolerability of CCR1 receptor antagonists in human clinical trials provide a rationale for using CCR1 antagonists as a new therapeutic target in ovarian and other cancers." (PMID 32963283, 2020). "Our major focus has been on the control of cancer cell Ccr1 and Ccr2 in CAF-FAK regulation of malignant cell metabolism as we detected the most significant increases in their ligands, Ccl6 and Ccl12, respectively." (PMID 32157087, 2020). "The role of CCL3 and its receptor CCR1 in bone metastasis have been best characterized in the context of MM and blockade of this receptor has promising effects in pre-clinical animal cancer models." (PMID 29930538, 2018). "In a genetically-engineered Apc+/∆716/Smad4+/− compound knockout mice that develop invasive intestinal adenocarcinomas, mouse CCL9 (mCCL9) is secreted from the cancer epithelium, which recruits CCR1+ myeloid cells to promote tumor invasion." (PMID 27136535, 2016). "Employing this model, we monitored the behavior of the Ccr1-mVenus+ cells in the cancer metastasis microenvironment first by histochemistry at 14 days post-injection." (PMID 25326065, 2014). "Namely, neutrophils found in the early phase of cancer cell dissemination expressed CCR1 exclusively and MMP9 preferentially, whereas fibrocytes accumulated in later phase expressed MMP2 exclusively." (PMID 25326065, 2014). "Additionally, the relationship exhibited by CCL3/5 and CCR1 was found to correspond with pro-inflammatory macrophage polarisation, which in turn facilitates the phagocytosis of cancer cells." (PMID 39901202, 2025). "CCL2 increased the expression level of the CCR1 ligand CCL3 in MAMs via CCR2, and the signaling generated by the CCL3/CCR1 interaction enhanced and stabilized the cancer cell-MAM interaction in part through integrin α4 binding to VCAM1 expressed on tumor cells in an autocrine manner." (PMID 37208442, 2023). "CCL5 also promotes angiogenesis, which is associated with an increase in vascular endothelial growth factor (VEGF) expression in cancer cells and vascular endothelial cells via the activation of C-C Motif Chemokine Receptor 1 (CCR1) and C-C Motif Chemokine Receptor 5 (CCR5)." (PMID 37895310, 2023). "Since HSPC-like cells are found in the cancer host in the periphery and intratumorally, express CCR1 and CCR5, and can be transfected by 4PD, we evaluated whether CCR1 and CCR5 blockade can affect the differentiation of HSPC-like cells into MDSCs." (PMID 35064009, 2022). "Chemokines (CCR1, CCR2, CCR3, CCR4, CCR5, CCR6, CCR7, and CCR8) and receptor genes (CXCL1-17, CCL1-14, CCL16-26) were positively associated with necroptosis levels in various cancers." (PMID 36170029, 2022). "However, the attractiveness of a CCR1 antagonist for MM and potentially other cancers and/or bone complications, cannot be ignored." (PMID 35399952, 2022). "CCL16, a ligand of CCR1, accelerates the anti-cancer impacts of DCs and macrophages." (PMID 34737767, 2021). "According to the scoring criteria as described in the Materials and Methods, 35% (39 out of 111 case), 19% (21 out of 111 cases), 65% (72 out of 111 cases) and 41% (45 out of 111 cases) were considered positive for CCL5 in stromal cells and CCR1, 3 and 5 in carcinoma cells, respectively." (PMID 33671956, 2021). "Furthermore, the immunoreactivity for CCR1, 3 and 5 was detected in the cytoplasm of carcinoma cells." (PMID 33671956, 2021). "The produced chemokines act as chemoattractants for anti-cancer TIL with CCR1 and CCR5." (PMID 33076281, 2020). "The cancer cell recruits macrophages through the CCL2→CCR2 axis; these macrophages then secrete CCL3, which causes the retention of these cells in the metastatic niche in an autocrine manner via CCR1." (PMID 33076281, 2020).
cancer (continued). "CCR1 activation enhanced the interaction between “metastasis associated macrophages” (MAM) and cancer cells in part through integrin α4 resulting in increased extravasation of cancer cells and metastasis." (PMID 32963283, 2020). "CCR1 is involved in the invasion and metastasis of several cancer types." (PMID 29212252, 2017). "Therefore, it would be worthwhile to test such CCR1 inhibitors in preventing cancer metastasis, because they have been already cleared from safety concerns." (PMID 27136535, 2016). "We demonstrated that chemokine receptor CCR1 expressed on the iMCs was responsible for their accumulation because one of its specific ligands CCL9 (corresponding to CCL15 in humans) was secreted from the cancer cells." (PMID 25326065, 2014). "We therefore asked whether simultaneously silencing fibroblast-secreted amphiregulin and cancer cell expressed CCR1 was more efficacious than blocking either alone." (PMID 24068959, 2013). "The majority of the genes identified here, including but not limited to CCR1, CCR2, CCR3, ENA78, GPCR, GRO1, GRO2/GRO3, IP10, IL-8, NAP-2, PF-4 have been recently shown to associate with the progression of various types of cancer." (PMID 22347499, 2012). "Thus, it is unclear whether the AKT-STAT3 axis drives transcriptional activation of CCR1 in diverse cancer cell types." (PMID 29212252, 2017). "Inhibitors targeting CCR1—such as BX471, J113863, UCB35625, and MLN-3897—have been widely explored in cancer intervention therapies with promising results." (PMID 40740234, 2025). "Other chemokine receptors, such as CCR1, CCR3, or CCR5, are significantly co-upregulated across different cancer subtypes." (PMID 38723607, 2024). "The results of the IHC assay and qPCR assay both showed that the expression levels of CCR1, CCR5, and CCR7 were significantly lower in HCC tissues, compared with para-carcinoma tissues." (PMID 38552222, 2024). "We observed that the expression levels of CCR1, CCR2, CCR5, and CCR7 were significantly lower in the HCC tissues in TCGA LIHC dataset and GSE14520 dataset, compared with para-carcinoma tissues." (PMID 38552222, 2024). "In particular, chemokines, including CXCL8, CXCL10, CXCL11, CXCL16, CCL26, and CCL7, as well as chemokine receptors, including CXCR3, CCR2, CCR5, and CCR1, were positively correlated with MRPL13 expression in various cancer types." (PMID 37827692, 2023). "CCL3 is a chemokine involved in various inflammatory responses through chemokine receptors (namely CCR1 and CCR5), and has a key role in several human diseases such as cancer and HIV infection." (PMID 36814903, 2023). "TGF-β can induce SMAD4 inactivation in cancer cells, recruit CCR1+ neutrophils through the CCL15/CCR1 axis and mediate the progression and metastases of CRC." (PMID 36230676, 2022). "We also speculate that in vivo endemic BL cells expressing CCR1 are prone to migrate toward ligand-expressing immune cells and ligand-rich blood organs, and therefore, in an immunocompromised state, dissemination of malignant cells may contribute to the pathogenesis of this cancer." (PMID 35408790, 2022). "It is reported that CCR1, CCR2, CCR3 and CCR5 are involved in CCL7‐mediated macrophage migration and contribute to various inflammatory diseases and cancer." (PMID 34189838, 2021). "CCL5 action is mediated through its receptors, C-C chemokine receptor (CCR) 1, CCR3 and CCR5, and carcinoma cells have different expression patterns of these chemokine receptors." (PMID 33671956, 2021). "Our findings indicate that CAF-FAK expression regulates the expression of chemokines Ccl6 and Ccl12, which through malignant cell Ccr1/Ccr2 activity and PKA activation can control cancer cell metabolism." (PMID 32157087, 2020). "If the cancer cell stops in the bone, CCL15, produced by the cancer cell, acts chemotactically on osteoclast precursors and osteoclasts, probably via CCR1 and CCR3." (PMID 33182504, 2020).